CXCR2 (C-X-C motif chemokine receptor 2)
Diseases named in the same sentence as CXCR2 in open-access papers (continued):
Sharing a sentence is not in itself a finding about the gene and the disease.
tumor (continued). "However, it is important emphasize that CXCR2 can also be expressed in stromal cells and by tumor cells." (PMID 27618112, 2016). "In a mouse model of pancreatic ductal adenocarcinoma, it was demonstrated that tumor progression could be suppressed using a CXCR2 inhibitor via dysregulation of stroma-tumor signaling." (PMID 27618112, 2016). "This indicated that the CXCL1–CXCR1/CXCR2 signalling regulates αSMA induction in ASCs, which might predetermine acquisition of their tumour-promoting properties." (PMID 27241286, 2016). "Recently, the CXCR2 receptor for the granulocyte- and platelet-derived ligand CXCL5/7 was shown to be important for recruitment of neutrophils to early metastatic niches, and CXCR2 inhibitors reduce the recruitment of granulocytes in primary tumor sites as well." (PMID 26966341, 2016). "However, some of the earlier research efforts have indicated the role of CXCR2 signaling in mediating autonomous growth of tumor cells in PC." (PMID 26771140, 2016). "Additionally, Lewis lung carcinoma cells-derived oxysterol plays a key role in the recruitment of CXCR2+ tumor-promoting neutrophils into tumor tissues." (PMID 27446967, 2016). "Taken together, these lines of evidence strongly support the theory that CXCR2 signaling might play an important role in KRAS-induced tumor cell-autonomous growth by directly contributing to its intracellular signaling during PDAC development and progression." (PMID 26771140, 2016). "Our data demonstrates that CXCR2 signaling mediates KRAS-induced PC growth and suggests that targeting CXCR2 signaling might be a feasible approach to inhibit KRAS(G12D)-induced PDAC tumor cell growth." (PMID 26771140, 2016). "In addition, small molecule antagonists of CXCR1 and CXCR2 inhibited liver metastasis of CRC by decreasing tumor angiogenesis and inducing tumor cell apoptosis in a mouse model." (PMID 27136535, 2016). "Elimination of Gr-1+ leukocytes in athymic nude mice slowed the growth of a variant of a UV light–induced tumour, and DMBA/TPA-treated mice that lack CXCR2, the chemokine receptor for KC and MIP-2, showed a reduced neutrophil chemotaxis and resistance to skin tumourigenesis." (PMID 26079427, 2015). "Therefore, we confirmed that CXCR2 expression on immune cells likely plays a vital role in tumor progression." (PMID 26503598, 2015). "In contrast to HSP27-mediated effects of SW480 cells on Cx43 expression, SW620 cell-secreted factors up-regulate the endothelial expression of Cx32 and enhance tube formation via a CXCR2, suggesting a promoting effect on angiogenesis and, consequently, tumor growth." (PMID 26320187, 2015). "Previous studies have reported roles for CXCR2 in tumor development." (PMID 26503598, 2015). "Moreover, activation of CXCR2 on Ras-transformed keratinocytes contributes to tumor progression in a mouse model of skin cancer." (PMID 25372289, 2014). "In addition, incubation of macrophages with a CXCR2 neutralizing antibody prevented the tumor-cell-induced macrophage migration." (PMID 24924428, 2014). "In this study, tumor cell inoculation increased CXCR2 expression in spinal neurons." (PMID 24580964, 2014). "This could be due to inhibition of additive direct effect of CXCR2 axis activation on tumor endothelial cells that leads to less tumor angiogenesis." (PMID 24321240, 2013). "Moreover, CXCR2 knockdown in hPTTG1-overexpressing MCF-7 tumors dramatically accelerated tumor growth and metastasis." (PMID 22789011, 2012). "In a mouse model, CXCR2-mediated senescence limited hPTTG1-induced tumor growth and metastasis." (PMID 22789011, 2012). "To explain our finding that p21 knockdown inhibited hPTTG1/CXCR2-induced senescence, we speculate that p21 is a critical downstream mediator that determines the role of CXCR2 in tumor development." (PMID 22789011, 2012). "CXCR2 has been shown to play critical roles in both tumor promotion and suppression." (PMID 22789011, 2012).
tumor (continued). "Other findings suggest that CXCL1 or CXCL8 signalling may reduce tumour growth by promoting senescence through CXCR2." (PMID 21298036, 2011). "Furthermore, the frequency of the CXCR2 (+1208) T allele was significantly higher in patients with a large tumor size (OR = 1.98; P = 0.0001), with high SBR tumor grade (grade 3) (OR = 1.67; P = 0.01), and with lymph node metastases (OR = 1.83; P = 0.0008)." (PMID 20540789, 2010). "Above median expression of CXCR2, CXCR3 and CCR1 in the tumour islets is associated with increased survival in NSCLC, and expression of CXCR3 correlates with increased macrophage and mast cell infiltration in the tumour islets." (PMID 20429924, 2010). "Moreover, CXCR1 and CXCR2 are implicated in tumour growth by directly enhancing tumour cell properties, thus indicating the possibility of manipulating CXCR1 and CXCR2 for future therapeutic intervention." (PMID 19401689, 2009). "In contrast to wild-type (WT), Fpr1-/-, and Fpr2-/- mice, neutrophils were almost completely absent in 4T1 tumors from Cxcr2-/- mice, indicating a dominant role for CXCR2 in the recruitment of tumor-associated neutrophils, leading us to use Cxcr2-/- mice for further studies." (PMID 41977328, 2026). "To assess whether CXCR2 is responsible for the differentiation of GFs into αSMA- or vimentin-expressing CAFs within tumors, we conducted immunofluorescence double staining of tumor tissues." (PMID 40490643, 2025). "In addition, NF‐κB signalling could also induce the secretion of CXCL1 and the recruitment of CXCR2 + MDSCs into CRC tumours, thus impairing effective T cell responses during anti‐PD1 therapy." (PMID 40122703, 2025). "However, the phagocytic activity of TAMs towards tumour cells was impaired after CXCR2 blockade." (PMID 41163221, 2025). "Consequently, blocking the CXCL1/CXCR2 signaling axis in tumor cells could be a promising approach to limit invasion and metastasis in a wide subset of CRC patients." (PMID 40943634, 2025). "Additionally, in a mouse model, VEGF‐A secreted by colorectal cancer cells stimulated the production of CXCL1 by TAM and recruited CXCR2+ MDSCs from the circulatory system into the premetastatic liver, further serving as support cells to maintain the survival of tumor cells with liver metastasis." (PMID 40452814, 2025). "Finally, the use of UM-SCC-11B and UM-SCC-74B cells transfected with siRNA targeting CXCR1 and CXCR2 further confirmed that removal of CXCR1/2 receptor signaling could sensitize HPV-negative HNSCC tumor cells to the cytotoxic activity of docetaxel in vitro." (PMID 39639338, 2024). "Finally, we conducted studies to determine whether expression of CXCR2 improved the anti-tumor activity of canine B7-H3 CAR T cells, using a mouse xenograft model of NSG mice implanted with canine OS cells." (PMID 38554158, 2024). "Furthermore, the simultaneous inhibition of CCR1 and CXCR2 expressed on myeloid cells can result in more robust suppression of tumor growth and metastasis, highlighting the potential of combinational therapeutic strategies targeting multiple chemokine receptors." (PMID 39795864, 2024). "Moreover, IG1 could be responsive for myeloid-targeted therapies as those based on CXCR2 (C-X-C motif chemokine receptor 2) and CSFR (colony-stimulating factor receptor) inhibitors to deplete or reprogram tumor-associated neutrophils and M2 macrophages." (PMID 39199659, 2024). "In addition to their effects on immune responses, MDSCs promote tumor development by secreting vascular endothelial growth factor (VEGF) and matrix metalloproteinase-9 (MMP9) to support tumor angiogenesis and expressing CXCR2 to promote the formation of pre-metastatic niche." (PMID 38609997, 2024). "Another proposed IO combination of CXCR2 (receptor crucial to neutrophil recruitment and highly expressed in NASH-HCC) and anti-PD1 treatment aimed at inhibiting tumour-associated neutrophils demonstrated reprogramming of the tumour immune microenvironment that promotes ICI in NASH-HCC." (PMID 38760445, 2024).
tumor (continued). "Moreover, CXCR2 was also expressed on the macrophage surface and found to mediate tumor invasion and metastasis, so we hypothesized that OSCC cell-derived CXCL1 may promote macrophages to secrete EGF via CXCR2." (PMID 38713320, 2024). "Although we previously demonstrated that disruption of CCR1-mediated myeloid cell accumulation suppressed tumor progression in syngeneic mouse models, it remains unclear whether disruption of CXCR2-mediated myeloid cell accumulation can suppress tumor progression." (PMID 38750114, 2024). "Patients exhibiting an enrichment of innate immune cells within the TME may respond positively to myeloid-targeted therapies such as C-X-C motif chemokine receptor 2 (CXCR2) and colony-stimulating factor receptor (CSFR) inhibitors, which aim to deplete or reprogram tumor-associated neutrophils." (PMID 39845973, 2024). "Therefore, it will be required to determine whether the CXCL8-CXCR1/CXCR2 axis will be a good target in personalized anti-tumor treatment." (PMID 36725964, 2023). "Furthermore, synergy of CXCR2 and anti-PD-1 inhibition led to the expansion of an intratumoural immature neutrophil population originating from either a neutrophil progenitor (NeP) or tumour-seeded hematopoietic stem cell." (PMID 37534829, 2023). "Moreover, CXCR1 and CXCR2 are differentially expressed in human tissues, though in mouse, CXCR2 is the predominant receptor mediating response to the murine chemokine ligands during inflammation, angiogenesis, and tumor growth (CXCL1,2,3 and 5, also known as KC, MIP2α, MIP2β, and LIX)." (PMID 37270599, 2023). "Moreover, in the Braf/Pten/Cxcr2WT mice, we might have observed an increase in tumor growth and incidence if 100% of the tumor cells were CXCR2 positive." (PMID 37270599, 2023). "CXCL1 could bind to CXCR2 on MDSCs and promote their migration to the tumor microenvironment." (PMID 37865804, 2023). "Taken together, our data from both tumor models and in vitro studies show that CXCR2 activation is associated with activation of the MAPK cascade, AKT, and WNT signaling, expression of chemokines that recruit MDSCs and pro-tumor macrophages, and enhanced tumor growth." (PMID 37270599, 2023). "In addition, a more recent study demonstrated that the small molecule PAD4 inhibitor JBI-589 can suppress primary tumour growth in mouse models by preventing neutrophil accumulation in the tumour microenvironment via downregulation of chemokine receptor CXCR2 expression." (PMID 37778382, 2023). "Therefore, we hypothesized that the CXCLs/CXCR2 axis mediates RT-induced neutrophilic infiltration of the tumor." (PMID 38067390, 2023). "This chimerism has likely impacted the significance of our results, as the chimerism could be associated with more Braf/Pten/Cxcr2−/− tumor formation than would have occurred if 100% of the GFP-positive tumor cells had been negative for CXCR2 expression." (PMID 37270599, 2023). "Moreover, the CXCL1/CXCR2 axis is still thought to be closely related to tumour resistance." (PMID 37037815, 2023). "Therefore, therapies targeting the CXCLs/CXCR2 axis and/or IL-1β signaling may increase the RT-mediated innate response and immune-modulation through shaping tumor-infiltrating neutrophil activity in the TME." (PMID 38067390, 2023). "In addition, CXCL8 may directly stimulate CXCR1- or CXCR2-expressing tumor (microenvironmental) cells, stimulating their survival, proliferation, and migration further enhancing tumor expansion." (PMID 36725964, 2023). "Interestingly, regarding CXCR2 that was expressed at similar levels in T, TA, and TAc, patients with higher CXCR2 expression in tumor samples presented reduced risk of recurrence independent of cancer cell presence in tumor surrounding." (PMID 36140779, 2022). "The anti-tumor effect of CXCR2 antagonist SCH-527123 may be produced by impairing CXCR2 signaling." (PMID 36612163, 2022).
tumor (continued). "Similarly, we predicted that CXCR2-mediated accumulation of the TANs in the stroma could be a pro-NETotic mechanism of the BrM to initiate tumor invasion." (PMID 35158784, 2022). "IL-8 is a chemokine that binds C–X–C motif chemokine receptor 1 (CXCR1) and CXCR2, which are G-protein coupled receptors displayed on granulocytes, monocytes, and endothelial cells to increase angiogenesis, recruit immunosuppressive cells to the tumor site, and worsen prognosis." (PMID 35565306, 2022). "Moreover, CXCR2 agonists are involved in tumor-supporting NET production." (PMID 36555469, 2022). "Based on these results, authors hypothesized that CXCR2 activation could be used by metastatic tumors as a mechanism to delay apoptosis and to program tumor-infiltrating NETs into a pro-NETotic state, to promote subsequent migration and invasion of metastatic tumor cells." (PMID 35884845, 2022). "CXCR2 signaling might exert a tumor-suppressive effect on CCA cells." (PMID 35377900, 2022). "Studies have shown that cancer-associated fibroblasts in primary tumours enhance tumour cell invasion by secreting cancer-associated fibroblast chemokine (C-X-C motif) ligand 1 (CXCL1) and interacting with C-X-C motif chemokine receptor 2 (CXCR2) in tumour cells." (PMID 35473583, 2022). "CXCR2 expression may be increased via transduction in lymphocytes isolated from the patient and when such transduced lymphocytes are reintroduced into the patient’s body, the cells will migrate to the tumor and destroy the tumor cells." (PMID 35216283, 2022). "In addition, CXCR2 has been shown to participate in the progression of different types of cancer, playing a significant role in proliferation, survival, and metastasis of tumor cells, and affecting the whole tumor microenvironment." (PMID 33953162, 2021). "However, CXCR2 mediated autocrine loop is also demonstrated in tumor pathology." (PMID 34108959, 2021). "Therefore, an anti-tumor effect of CXCR2 inhibition in RET transgenic mice could be mediated by reduced migration of CXCR2+ PMN-MDSC to the tumor, resulting in the accumulation of NK cells." (PMID 33578808, 2021). "Thus, blocking infiltration of polymorphonuclear-MDSCs and TANs in the tumor microenvironment by CXCR2 inhibitors may provide a safe and promising treatment option in cancer immunotherapy." (PMID 34885241, 2021). "Moreover, anti-CXCR2 therapy induced an accumulation of NK cells in the tumor microenvironment." (PMID 33578808, 2021). "Additionally, antagonism of CXCR2 (danirixin) could promote tumor progression more effectively than CXCR1/2 (reparixin) in CT26 tumor model." (PMID 34025668, 2021). "Moreover, AUC for CXCL8 was higher than for CXCR2 and classical tumor markers." (PMID 34680333, 2021). "Also, blocking the CXCL8 and its receptors (CXCR1 / CXCR2) appears to be a novel therapeutic strategy that may reverse the tumor cell metastatic phenotype in patients with ESCCs." (PMID 33390169, 2021). "At the same time, there was a large overlap between the genomes of PMN-MDSCs and M-MDSCs involved in immunosuppression, such as IL-1B, ARG-2, CD84, and WFDC17, and chemokine receptors, such as CCR2 and CXCR2, revealing that MDSCs could be migrated to the primary tumor by tumor-derived chemokines." (PMID 34527668, 2021). "Blockade of CXCLs/CXCR2 signal might indirectly induce senescence of tumor cell." (PMID 33814009, 2021). "In addition, based on the correlation results, CXCR2 WT and cKO mice could favorably induce tumor and ascites burdens, respectively, playing a critical role in OC survival." (PMID 34638514, 2021). "In addition, combination of CSF-1R and CXCR2 inhibitors resulted in strong anti-tumor effect." (PMID 35127700, 2021). "Analysis of pharmacodynamic markers within harvested PTEN-deficient tumour samples similarly indicated IR to induce the expression of Bcl-2, a known mediator of RT resistance in a number of cancer models, but that this was attenuated by inhibition of CXCR1/CXCR2 signalling." (PMID 32743555, 2020).
tumor (continued). "Similarly, loss of CXCR2 in a colitis-associated cancer mouse model dramatically inhibited tumorigenesis through inhibiting infiltration of PMN-MDSCs into colonic mucosa and the tumor site." (PMID 32509781, 2020). "Indeed the use of intratumoral injections of IL-33 promotes antitumor activity of ILC2s either through IL-5 and GM-CSF, which control tumor growth, through the recruitment of eosinophils or through the production of CXCR2 ligands with lytic activity on CXCR2+ tumor cells." (PMID 33233582, 2020). "In mice engrafted with wild-type EO771 cells, treatment with a Cxcr2 antagonist inhibited tumor growth, reduced myeloid suppressor and regulatory T cells with concomitant increases in macrophages, dendritic cells, and natural killer cells, and reduced tumor infiltration of CD8+ T cells." (PMID 32499871, 2020). "Interestingly, CXCL5, a chemokine known for its role in promoting the recruitment of MDSCs and TAMs towards tumor sites and its receptor CXCR2 in addition to the Tregs transcription factor FOXP3 were among the highly differentially expressed between the XRT group and XRT + GLZ group." (PMID 31015520, 2019). "Therefore, the anti-tumor effects of CXCR2 inhibitors that influence neutrophil infiltration may unintentionally promote tumor growth." (PMID 31788042, 2019). "Thus, inhibiting CXCR2 expression may alter the tumor microenvironment and attenuate tumor progression." (PMID 31395859, 2019). "To test whether LEC-derived chemokines play a role in MDSC recruitment, we collected tumors, and tumor-draining and distant lymph nodes from mice that received vehicle or CXCR2-antagonist SB225002 treatments, and quantified the amount of CD11b+/Gr-1+ MDSCs in those tissues by flow cytometry." (PMID 31390756, 2019). "Thus, targeting CXCR2, particularly in combination with immune checkpoint inhibitors, may offer new opportunities to slow or reverse cancer progression across multiple tumor types, as the approaches act via complementary anti-tumor pathways." (PMID 30800123, 2019). "The mean tumor volume 34 days after tumor implantation was 2926 mm3 for controls, 1756 mm3 for DC treated mice, 930.7 mm3 for sarcosine treated DC treated mice, 1778 mm3 for sarcosine treated DCs plus anti-CXCR2 treated mice, and 3111 mm3 for anti-CXCR2 treated mice." (PMID 31753028, 2019). "Therefore, CXCR2 may have different functions in normal, precancerous and tumor cells and requires further investigation." (PMID 31788042, 2019). "Furthermore, STAT3 phosphorylation was also decreased in the GMPs of CXCR2-/- tumor-bearing mice." (PMID 31395859, 2019). "Thus, the inhibition of CXCR2 or its downstream signaling pathways could significantly attenuate tumor progression." (PMID 31788042, 2019). "In keeping with the critical role of IL-8 in cancer stemness, a function-blocking antibody against its receptor, CXCR-1, or a small-molecule inhibitor of CXCR-1 and CXCR-2, repertaxin, could deplete CSCs and inhibit tumor aggressiveness in human breast cancer xenografts." (PMID 31417869, 2019). "Given the dramatic effect of CSF1R inhibition as a single agent compared to our previous work on CXCR2 inhibition where efficacy in late-stage tumors was only observed in combination with anti-checkpoint inhibition, we wanted to compare the effect of these inhibitors on tumor gene expression." (PMID 29719257, 2018). "Furthermore, expression of its alternate receptor CXCR2 was observed in tumor cells only." (PMID 30086759, 2018). "Consistently, blockade of CXCR2 systemically in mice instead of tumor cells only could reduce engraftment rates of tumor cells homing to liver after IR injury, indicating that CXCL1/CXCR2 signaling is critical in PARP-1-induced susceptibility of the liver to recurrence." (PMID 29179487, 2017). "In addition, CXCR2 was mainly expressed along tumor cell membrane." (PMID 28415702, 2017).